EFHD2 (EF-hand domain family member D2)
Diseases named in the same sentence as EFHD2 in open-access papers (continued):
Sharing a sentence is not in itself a finding about the gene and the disease.
triple-negative breast carcinoma (1 paper, 2024). An invasive breast carcinoma which is negative for expression of estrogen receptor (ER), progesterone receptor (PR), and human epidermal growth factor receptor 2 (HER2). "Consequently, EFHD2 supports the migration and invasion of triple-negative breast cancer cells." (PMID 38346956, 2024).
ulcerative colitis (1 paper, 2024). An inflammatory bowel disease involving the mucosal surface of the large intestine and rectum. "Overall, the expression pattern and level of EFHD2 in the intestinal epithelium might be predictive of responsiveness to anti-TNF therapy of ulcerative colitis." (PMID 38346956, 2024). "Therefore, EFHD2 might be a potential predictor to guide the clinical treatment of ulcerative colitis with anti-TNF therapy." (PMID 38346956, 2024). "Here, we report that EF-hand domain-containing protein D2 (EFHD2), highly expressed in normal intestine tissues but decreased in intestinal biopsy samples of ulcerative colitis patients, protects intestinal epithelium from TNF-induced IEC apoptosis." (PMID 38346956, 2024).
cancer (13 papers, 2009 to 2024). A tumor composed of atypical neoplastic, often pleomorphic cells that invade other tissues. "In cancer EFHD2 has been associated with tumour invasion thus showing a potential interest as therapeutic target but the molecular mechanisms at the basis of these observations are less known than those related to TKS4 and TKS5." (PMID 36932446, 2023). "Previous studies have implicated EFHD2/Swip-1 in a number of cellular processes ranging from adhesion turnover, cell spreading and migration, B cell receptor signaling, and cancer invasion." (PMID 35524157, 2022). "EFhd2 is a conserved calcium binding protein linked to different neurological disorders and types of cancer." (PMID 27064956, 2016). "EFhd2 has also been associated with different pathological processes, from cancer to neurological disorders." (PMID 27064956, 2016). "EFHD2 enhances invadopodia formation by modulating actin dynamics, thereby increasing cancer invasion and metastasis." (PMID 39458997, 2024). "In this study, we utilized cancer database analysis and a cohort using an IHC approach to examine the correlation between EFHD2 and cancer recurrence." (PMID 29097801, 2017). "We demonstrated that the mechanism of EFHD2 in enhancing EMT occurs partly through inhibition of caveolin-1 (CAV1) for cancer progression." (PMID 29097801, 2017). "In cancer, EFhd2 was found to be overexpressed in the majority of carcinomas, colon cancer, and melanoma." (PMID 27064956, 2016). "Moreover, EFHD2 garners attention for its indispensable role in activating immune cells and promoting cancer dissemination." (PMID 39026674, 2024). "EFhD2/Swip-1 was found significantly upregulated in a number of pathological conditions of inflammation, immune response, and cancer suggesting an important role of EFhD2/Swip-1 in cell migration and cell adhesion during immune cell response and cancer invasion." (PMID 35524157, 2022). "EFhd2 has also facilitates F-actin remodeling necessary for migration and invasion of cancer cells." (PMID 31456657, 2019). "Although the role of calcium signaling dysregulation in cancer cells is still poorly understood, increases in calcium levels could be the driving force to facilitate the effect of EFhd2 on nucleation and polymerization of actin filaments." (PMID 31456657, 2019). "Until recently, EFHD2 was recognized to function in cancer metastasis." (PMID 29097801, 2017). "Thus, even though the role that EFhd2 plays in cancer biology is of great interest, this review focusses on EFhd2's role in the central nervous system, specifically its association with AD and other neurological disorders." (PMID 27064956, 2016). "The results indicated that EFhd2 may mediate invasion and metastasis of cancerous cells, suggesting it plays an important role in the biology of cancer." (PMID 27064956, 2016). "In this example, the overexpression of Efhd2 (also commonly known as swiprosin-1) is not a surprising finding, in that it encodes for a calcium ion binding protein involved in several cellular functions, including neurodegeneration and cancer." (PMID 31757200, 2019). "This analysis revealed that EFHD2 expression did not correlate with cancer malignancy." (PMID 29097801, 2017).
tumor (8 papers, 2011 to 2024). "The hub genes of the network included SLC2A1 (solute carrier family 2 member 1), CDH3 (cadherin 3), and EFHD2 (EF-hand domain family member D2), whose expression increased with tumor stage and was associated with a lower survival rate." (PMID 39199659, 2024). "Among the hub genes, SLC2A1, CDH3 and EFHD2 increased across tumour stages and were associated with poorer survival probability, suggesting their critical roles in iCCA." (PMID 34013637, 2021). "EFHD2, whose function in malignancies remained unexplored, was reported to stimulate tumour invasion and metastasis." (PMID 34013637, 2021). "Key hub genes SLC2A1, CDH3 and EFHD2 showed increased expression across the tumour stage and were correlated with poor survival, whereas decrease of FAM171A1, ONECUT1 and PHYHIPL was correlated with better survival." (PMID 34013637, 2021). "We postulate that EFHD2 acts as tumour‐promoting gene probably through inducing chromosome separation errors or O‐glycan modification of key adhesion proteins and proteases that are associated with metastasis." (PMID 34013637, 2021). "Taken together, these findings indicate that CDH3 and EFHD2 can activate these pathways to promote tumour progression." (PMID 34013637, 2021). "The result revealed that only EF-hand domain-containing protein D2 (EFHD2) exhibited high expression in all highly metastatic tumor cell lines." (PMID 29097801, 2017). "In the present study, the novel protein EF-hand domain-containing protein D2 (EFHD2) was identified as expressed in highly metastatic tumor cells." (PMID 29097801, 2017). "Western blot validation revealed that EFHD2 was expressed at higher levels in tumor cells with more metastatic ability compared with those with less metastatic ability." (PMID 29097801, 2017). "Among the hub genes, SLC2A1, CDH3 and EFHD2 displayed increased expression across the tumour stage." (PMID 34013637, 2021). "The finding of EFHD2 was based on our originally risky hypothesis; thus, we assessed whether the hypothesis was applicable to other types of tumor cells." (PMID 29097801, 2017). "In the present study, we hypothesized that tumor cells use a similar mechanism to promote metastasis at a very early stage of disease and accordingly identified EFHD2 from highly metastatic tumor cell lines." (PMID 29097801, 2017). "As a result, we identified CDH3, EFHD2 as tumour‐promoting genes, and ONECUT1, PHYHIPL as tumour suppressing genes." (PMID 34013637, 2021). "Surprisingly, only one candidate, namely, EF-hand domain-containing protein D2 (EFHD2), exhibited overexpression in all highly metastatic tumor cell lines." (PMID 29097801, 2017). "Therefore, it is reasonable to generate and cross EFhd2 knockout and transgenic mice with the respective Efhd1 mice and analyze the impact in function and development, especially with regard to the immune and nervous system, as well as the progression of tumours." (PMID 21244694, 2011). "Interestingly, most CIDGS-related genes, such as XRCC6, ST13, PES1, EFHD2, APOL2, ACTR2, and CDCP1, were markedly upregulated in HNSCC tumor samples, whereas several other genes, such as MARCO, MRC1, and CD83, were upregulated in healthy samples." (PMID 38666027, 2024). "Finally, significant negative associations between expression of EFHD2, PHYHIPL and promoter DNA methylation were detected, and alterations of DNA methylation were correlated with tumour survival." (PMID 34013637, 2021).
neurodegenerative disease (6 papers, 2011 to 2023). A disorder of the central nervous system characterized by gradual and progressive loss of neural tissue and neurologic function. "The data provide further evidence that EFhd2 shares molecular and biochemical characteristics with known intrinsically disordered proteins associated with neurodegenerative diseases." (PMID 31456657, 2019). "EFHD2 gene, target of miR-487b, is a Ca2+ binding protein that shows a predominant level of expression in the central nervous system, its deregulation is linked to the development of neurodegenerative diseases and synaptic disorders." (PMID 36932446, 2023). "In addition to its association with neurodegenerative diseases, Efhd2 gene expression has also been found altered in psychiatric disorders." (PMID 27064956, 2016). "Whether all these data represent a causative connection of EFhd2 with neurodegenerative diseases on the one hand, with neuronal regeneration on the other hand or are merely secondary effects is not known at present." (PMID 21244694, 2011). "Given the increasing incidence of neurodegenerative diseases, it would potentially be important to examine EFhd2 expression and function in human inflammatory diseases, including neuroinflammatory processes, and in murine mouse models for these diseases." (PMID 21244694, 2011). "This suggests that EFhd2 may play an important role in the pathophysiology of neurodegenerative diseases." (PMID 31456657, 2019). "How EFhd2 may be linked with neurodegenerative diseases is not known, due to the physiological function of EFhd2 being poorly understood." (PMID 25133820, 2014). "Thus it is tempting to speculate that EFhd2 might be involved in transport of cargo relevant for neurodegenerative diseases, in combination with or without tau." (PMID 25133820, 2014).
neurological disorders (6 papers, 2014 to 2025). "EFhd2 altered protein abundance and its association with pathological proteins have also been found in other neurological disorders." (PMID 27064956, 2016). "Besides, EFHD2 is implicated in neurological disorders, including AD, and regulates macrophage function in GBM, presenting potential for immunotherapy." (PMID 40018519, 2025). "Identification of EFhd2 associated with neurological disorders." (PMID 27064956, 2016). "The function of EFhd2's polyalanine motif is still unknown, but proteins containing polyalanine expansions have been shown to be linked to different neurological disorders." (PMID 27064956, 2016). "Recent studies demonstrated that EFhd2 has structural characteristics similar to amyloid proteins found in neurological disorders." (PMID 27064956, 2016). "EFhd2 gene expression and protein abundance have been also shown to be altered in AD and other neurological disorders." (PMID 27064956, 2016). "Nevertheless, further studies are crucial to determine the role that EFhd2 plays in the pathophysiology of neurological disorders." (PMID 27064956, 2016). "The studies of the pathological role of EFHD2 therefore have focused on behavioral pathologies, neurological disorders, and neurodegenerative diseases, highlighting the role of EFHD2 in regulating the membrane-cytoplasm trafficking of membrane-associated proteins." (PMID 38346956, 2024). "Alternatively, EFhd2 altered expression in neurological disorders could be related to neuroprotection." (PMID 27064956, 2016). "However, the specific role that EFhd2 plays in the pathophysiology of neurological disorders is still poorly understood." (PMID 27064956, 2016). "Further characterization of EFhd2’s role in AD and other neurological disorders could lead to better understanding of the transition from physiological to pathological protein conformations that could serve as the basis for the identification of therapeutic strategies." (PMID 31456657, 2019). "However, the phenotype of induced neurodegeneration, or other neurologic diseases, upon genetic or environmental challenge, might be modulated in one or the other direction in the absence of EFhd2." (PMID 25133820, 2014).
EFHD2 also shares sentences with these, for which no sentence is quoted: frontotemporal lobar degeneration (5 papers); amyotrophic lateral sclerosis (3); dementia (3); adenocarcinoma (2); acne (1); asthma (1); atherosclerosis (1); atopic dermatitis (1); autoimmune disease (1); bacterial infection (1); brain tumours (1); colon cancer (1); COVID-19 (1); depression (1); epilepsy (1); gastric cancer (1); glomerulosclerosis (1); Huntington disease (1); Hyperglycemia (1); ischemia (1); lung squamous cell carcinoma (1); motion sickness (1); myocardial infarction (1); pancreatic cancer (1); Parkinson’s (1); psychiatric disorder (1); renal carcinoma (1); Salmonella Infections (1); squamous cell carcinoma (1); Stroke (1).
A further 1 disease shares a sentence with EFHD2 in 1 paper.